TUBE1 (tubulin epsilon 1)
Synonyms: TUBE; dJ142L7.2; FLJ22589
Tractability: Small molecule: it belongs to a druggable protein family. PROTAC: ubiquitination databases record sites on it.
Gene: Protein-coding gene on chromosome 6 (112,070,663 to 112,087,529, reverse strand). Ensembl gene ENSG00000074935.
Subcellular location: Cytoplasm, cytoskeleton, microtubule organizing center, centrosome
Gene Ontology:
Molecular function: GTP binding; structural constituent of cytoskeleton
Biological process: cytoskeleton organization; microtubule cytoskeleton organization; centrosome cycle; mitotic cell cycle; microtubule-based process
Cellular component: centrosome; pericentriolar material; microtubule; microtubule cytoskeleton
Genetic constraint (gnomAD): Loss-of-function variants: 25 observed, 40.34 expected, observed/expected ratio (o/e) 0.62, 90% interval 0.45 to 0.87. The upper end of that interval is the gene's LOEUF score, 0.87, which puts it in group 3 of 6, group 1 being the genes least tolerant of losing a copy. Missense variants: 429 observed, 443.3 expected, observed/expected ratio (o/e) 0.97, 90% interval 0.89 to 1.05. Synonymous variants: 148 observed, 155.22 expected, observed/expected ratio (o/e) 0.95, 90% interval 0.83 to 1.09.
Homologues: Orthologues: chimpanzee TUBE1 (99% identical), macaque TUBE1 (98% identical), dog TUBE1 (94% identical), pig TUBE1 (93% identical), guinea pig TUBE1 (92% identical), mouse Tube1 (91% identical), rat Tube1 (91% identical), rabbit TUBE1 (90% identical), tropical clawed frog tube1 (81% identical), zebrafish tube1 (74% identical). Paralogues in human: TUBB4B (34% identical), TUBB8 (34% identical), TUBB (33% identical), TUBB4A (33% identical), TUBB8B (33% identical), TUBB2B (33% identical), TUBB3 (33% identical), TUBB6 (33% identical), TUBB2A (33% identical), TUBB1 (32% identical), TUBA8 (29% identical), TUBA3C (28% identical), and 11 more.
Diseases named in the same sentence as TUBE1 in open-access papers:
TUBE1 is named in the same sentence as 13 diseases in open-access papers, as found by Europe PMC text mining. Sharing a sentence is not in itself a finding about the gene and the disease. The quoted sentences say what the papers report.
heart failure (1 paper, 2017). Inability of the heart to pump blood at an adequate rate to meet tissue metabolic requirements. "The modules related to cytoskeleton organization were detected specifically in heart failure arising from DCM, with increased KIF18A and TUBE1." (PMID 29160422, 2017).
melanoma (1 paper, 2022). A malignant, usually aggressive tumor composed of atypical, neoplastic melanocytes. "The genes of HAMP, SLC7A5, CYBB, and IFNG were highly expressed in melanoma cell lines, while JDP2, TUBE1, PROM2, GPX2, FBXW7, and ARNTL were lowly expressed in melanoma cell lines." (PMID 35373463, 2022).
skin cutaneous melanoma (1 paper, 2022). "TUBE1 encodes a tubulin superfamily member that was included in a ferroptosis prognostic model of skin cutaneous melanoma." (PMID 36414988, 2022).
tumor (3 papers, 2022 to 2023). "There is no report about the relationship between TUBE1 and tumor in the literature." (PMID 35610340, 2022).
TUBE1 also shares sentences with these, for which no sentence is quoted: bipolar disorder (1 paper); cancer (1); COVID-19 (1); Epstein-Barr virus infection (1); legionellosis (1); malaria (1); pancreatic cancer (1); schizophrenia (1); systemic lupus erythematosus (1).